BTNL10P (butyrophilin like 10, pseudogene)
Synonyms: BUTR1; BTN4; formerly BTNL10
Gene: Transcribed unitary pseudogene on chromosome 1 (228,510,425 to 228,512,305, reverse strand). Ensembl gene ENSG00000215811.
Subcellular location: Membrane
Diseases named in the same sentence as BTNL10P in open-access papers:
BTNL10P is named in the same sentence as 1 disease in open-access papers, as found by Europe PMC text mining. Sharing a sentence is not in itself a finding about the gene and the disease.
BTNL10P shares sentences with these, for which no sentence is quoted: tumor (1 paper).